COL25A1 (collagen type XXV alpha 1 chain)
Description:
Inhibits fibrillization of amyloid-beta peptide during the elongation phase. Has also been shown to assemble amyloid fibrils into protease-resistant aggregates. Binds heparin.
Synonyms: AMY; CLAC; CFEOM5; CLAC-P; CLACP
Tractability: Antibody: its Gene Ontology location is reachable by antibodies, with high confidence; UniProt predicts a signal peptide or a membrane-spanning region.
Gene: Protein-coding gene on chromosome 4 (108,808,725 to 109,302,752, reverse strand). Ensembl gene ENSG00000188517.
Subcellular location: Membrane
Subcellular location (Human Protein Atlas): Cytosol; Vesicles; Endoplasmic reticulum
Pathways (Reactome):
Extracellular matrix organization: Collagen biosynthesis and modifying enzymes; Collagen chain trimerization; Collagen degradation
Gene Ontology:
Molecular function: amyloid-beta binding; heparin binding; extracellular matrix structural constituent conferring tensile strength
Cellular component: extracellular matrix; extracellular region; plasma membrane; collagen type XXV trimer; endoplasmic reticulum lumen; membrane
Genetic constraint (gnomAD): Loss-of-function variants: 55 observed, 66.61 expected, observed/expected ratio (o/e) 0.83, 90% interval 0.66 to 1.03. The upper end of that interval is the gene's LOEUF score, 1.03, which puts it in group 4 of 6, group 1 being the genes least tolerant of losing a copy. Missense variants: 493 observed, 555.53 expected, observed/expected ratio (o/e) 0.89, 90% interval 0.82 to 0.96. Synonymous variants: 197 observed, 196 expected, observed/expected ratio (o/e) 1.01, 90% interval 0.89 to 1.13.
Homologues: Orthologues: chimpanzee COL25A1 (99% identical), macaque COL25A1 (98% identical), pig COL25A1 (94% identical), rabbit COL25A1 (93% identical), dog COL25A1 (93% identical), guinea pig COL25A1 (93% identical), mouse Col25a1 (93% identical), rat Col25a1 (91% identical), tropical clawed frog col25a1.2 (75% identical). Paralogues in human: COL23A1 (45% identical), COL11A1 (42% identical), COL5A1 (42% identical), COL11A2 (41% identical), COL2A1 (40% identical), COL4A5 (39% identical), COL4A1 (39% identical), COL5A2 (39% identical), COL5A3 (38% identical), COL1A1 (37% identical), COL4A2 (37% identical), COL7A1 (37% identical), and 25 more.
Diseases named in the same sentence as COL25A1 in open-access papers:
COL25A1 is named in the same sentence as 26 diseases in open-access papers, as found by Europe PMC text mining. Sharing a sentence is not in itself a finding about the gene and the disease. The quoted sentences say what the papers report.
Alzheimer disease (4 papers, 2013 to 2023). A progressive, neurodegenerative disease characterized by loss of function and death of nerve cells in several areas of the brain leading to loss of cognitive function such as memory and language. "For example, COL25A1 is brain-specific membrane-bound collagen that comprises an extracellular collagen domain associated with senile plaques in Alzheimer’s disease (AD; MIM 104300)." (PMID 34143809, 2021). "Gene COL25A1 is brain-specific membrane-bound collagen, containing extracellular collagen domains that associate with senile plaques in Alzheimer disease." (PMID 34143809, 2021). "There is genetic association to the amyloid plaque associated protein COL25A1 in Alzheimer's disease." (PMID 31183373, 2019). "COL25A1, a brain-specific collagen, was implicated in risks for Alzheimer's disease and antisocial personality disorder." (PMID 23966865, 2013). "Collagen XXV α 1 (COL25A1), the extracellular matrix gene, is a collagenous type II transmembrane protein, which was first purified from senile plaques of Alzheimer’s disease (AD) brains." (PMID 36980911, 2023). "Overexpression of the Col25a1 gene in neurons of transgenic mice leads to Alzheimer's disease-like brain pathology." (PMID 31183373, 2019).
Senile plaques (3 papers, 2021 to 2024). Senile plaques are extracellular deposits of amyloid in the gray matter of the brain. "Prior studies in murine models suggested that CLAC, a derivative of COL25A1, plays a pivotal role in converting diffuse Aβ deposits into senile plaques." (PMID 39070643, 2024).
breast tumors (2 papers, 2022 to 2024). "Collagen type XXV alpha 1 chain (Col25a1) was identified in mouse breast tumors but not in normal breast tissues." (PMID 36547361, 2022).
Akinesia (1 paper, 2023). Inability to initiate changes in activity or movement and to perform ordinary volitional movements rapidly and easily. "Pat-1001 is a fetus with fetal akinesia who was found on RES to be homozygous for a LOF variant in COL25A1 (NM_001256074.2:c.1517del:p.Pro506HisfsTer25)." (PMID 37344829, 2023).
arthrogryposis (1 paper, 2025). A rare, non-progressive congenital disorder characterized by multiple joint contractures which are present at birth. "Biallelic variants in COL25A1 have been associated with isolated congenital cranial dysinnervation disorders (CCDDs) and arthrogryposis multiplex congenital (AMC) with or without CCDD." (PMID 40158061, 2025).
Congenital ptosis (1 paper, 2025). Congenital ptosis is characterized by superior eyelid drop present at birth. "Two primary candidate genes, ZFHX4 [MIM:606940] and COL25A1 [MIM:610004], have been implicated in isolated congenital ptosis." (PMID 40410591, 2025). "Mutations in COL25A1 are also linked to congenital fibrosis of the extraocular muscles [MIM:616219], resulting in clinical manifestations such as congenital ptosis and abnormal development of extraocular muscles, which can impair eye movement and potentially cause blindness." (PMID 40410591, 2025).
dilated cardiomyopathy (1 paper, 2024). Cardiomyopathy which is characterized by dilation and contractile dysfunction of the left and right ventricles. "Abnormal development and functioning of the heart that results from mutations in ECM-related genes may lead to dilated cardiomyopathy and hypoplastic left heart syndrome, such as COL25A1 or COL1A2." (PMID 39202774, 2024). "In endothelial cells COL25A1 (Collagen Type XXV Alpha 1 Chain, 610004) is shown to be an effective gene signature for dilated cardiomyopathy, also predicted by LightGBM." (PMID 39202774, 2024). "Endothelial cell analysis further revealed COL25A1, NFIB, and KLF7 as significant genes for dilated cardiomyopathy, hypertrophic cardiomyopathy, and Tetralogy of Fallot." (PMID 39202774, 2024).
Duane retraction syndrome (1 paper, 2022). Duane retraction syndrome (DRS) is a congenital form of strabismus characterized by horizontal eye movement limitation, globe retraction and palpebral fissure narrowing in attempted adduction. "Fourth, given the phenotype overlap between CFEOM-5 and Duane retraction syndrome (DRS), another CCDD subset, whether COL25A1-related ocular abnormalities can be subtyped as CFEOM-5 remains to be discussed." (PMID 36360333, 2022).
ischemia (1 paper, 2022). A hypoperfusion of the BLOOD through an organ or tissue caused by a PATHOLOGIC CONSTRICTION or obstruction of its BLOOD VESSELS, or an absence of BLOOD CIRCULATION. "Contrarily, Col6a6, Col13a1, and Col25a1 genes showed no augmentation in mRNA expression at chronic phases of ischemia." (PMID 36555255, 2022).
multiple sclerosis (1 paper, 2013). A progressive autoimmune disorder affecting the central nervous system resulting in demyelination. "In contrast, the overexpression of the collagenous type II transmembrane protein (COL25A1) leads to AD-like pathology and different collagens, including COL1A1 and COL3A1, are induced in multiple sclerosis lesions." (PMID 23497022, 2013).
osteosarcoma (1 paper, 2024). A usually aggressive malignant bone-forming mesenchymal neoplasm, predominantly affecting adolescents and young adults. "Although not directly linked to osteosarcoma, COL25A1 expression has been studied as a potential pancancer prognostic indicator alongside other collagen family genes." (PMID 39701601, 2024).
Parkinson disease (1 paper, 2022). A progressive degenerative disorder of the central nervous system characterized by loss of dopamine producing neurons in the substantia nigra and the presence of Lewy bodies in the substantia nigra and locus coeruleus. "Future studies may address the investigation of col4a1 and col25a1 protein distribution and molecular pathways to generate Alzheimer’s or Parkinson’s disease models." (PMID 35163698, 2022).
tumor (6 papers, 2019 to 2023). "The ECM-related genes, DCN, COL11A1, LAMC3, and COL25A1, were also significantly downregulated in PVTT, compared with primary tumor tissues, indicating that the ECM is involved in macrovascular invasion by HCC." (PMID 34504839, 2021). "On the other hand, Col4a1, Col4a3, Col4a5, Col5a3, Col11a2, Col14a1, Col15a1, Col16a1, and Col22a1 were found in normal ECM but not in tumor ECM; Col25a1 was found only in tumor ECM but not in normal ECM." (PMID 36547361, 2022).
cancer (3 papers, 2020 to 2023). A tumor composed of atypical neoplastic, often pleomorphic cells that invade other tissues. "In SHH, we identified DMPs in four genes (CDK6, COL25A1, MMP16, PRIM2) that encode proteins which are the target of therapies in clinical trials for other cancers." (PMID 37035203, 2023). "Genes in PE‐Sor that have not been as strongly linked to cancer (COL25A1 and LHX8) did not change model accuracy to the same extent (<10%) when removed." (PMID 34766125, 2020). "Notably, COL25A1 is dysregulated and expressed in KIRC, LUAD, SARC, THCA, and UCEC cancer types." (PMID 37414817, 2023).
neurodegenerative disease (1 paper, 2022). A disorder of the central nervous system characterized by gradual and progressive loss of neural tissue and neurologic function. "Overall, our findings encourage further investigation on the role of col4a1 and col25a1 in the biology of the vertebrate brain as well as the onset of aging and neurodegenerative diseases." (PMID 35163698, 2022). "Our work may stimulate further investigation on the role of col4a1 and col25a1 in the onset of neurodegenerative diseases, and more in general in the aging process." (PMID 35163698, 2022).
COL25A1 also shares sentences with these, for which no sentence is quoted: arthrogryposis multiplex congenita (1 paper); breast carcinoma (1); connective tissue disorder (1); fibrosis (1); hepatocellular carcinoma (1); hypertrophic cardiomyopathy (1); hypoplastic left heart syndrome (1); macular degeneration (1); microcephaly (1); retinitis pigmentosa (1); Tetralogy of Fallot (1).